CCNH (cyclin H)
Diseases named in the same sentence as CCNH in open-access papers (continued):
Sharing a sentence is not in itself a finding about the gene and the disease.
hepatocellular carcinoma (1 paper, 2019). A malignant tumor that arises from hepatocytes. "Among 8 fusion genes, MAN2A1-FER, TRMT11-GRIK2 and CCNH-C5orf30 appear most frequently in hepatocellular carcinoma samples." (PMID 31164957, 2019).
Lung squamous cell carcinoma (1 paper, 2021). "We observed that the high expression of CCNH was significantly associated with shorter disease-free survival both in patients with LUAD and Lung squamous cell carcinoma (LUSC)." (PMID 33777168, 2021).
Lynch syndrome (1 paper, 2013). An autosomal dominant hereditary neoplastic syndrome characterized by the development of colorectal carcinoma and a high risk of developing endometrial carcinoma, gastric carcinoma, ovarian carcinoma, renal pelvis carcinoma, and small intestinal carcinoma. "Lynch syndrome tumors showed up-regulation of 1129 genes, e.g. genes involved in G1/S transition (CCNE, CCNH, E2F2 and CDK2), DNA replication (CDC45, RPA1, RFC5, MCM4 and POLD3) and chromosomal organization and mitosis (CCNB2, MLF1IP, CASC5, KIF2C and PLK4), which is in line with previous findings." (PMID 23951239, 2013).
malaria (1 paper, 2017). Malaria is a serious and sometimes fatal disease caused by a parasite that commonly infects a certain type of mosquito which feeds on humans. "Biochemically, it retains a dependence on cyclins for kinase activity, and in vitro, it is promiscuously activated by the malaria parasite cyclins PfCyc1 and PfCyc3, as well as the mammalian cyclin A, cyclin H, p25, and the Xenopus RINGO." (PMID 28611247, 2017). "Consistent with bioinformatic predictions, coimmunoprecipitation of PfCyc1 demonstrated that the PfCyc1/PfMAT1/PfMRK trimeric complex is preserved in malaria parasites, and is similar in constituents to the cyclin H/MAT1/Cdk7 complex." (PMID 28611247, 2017).
osteosarcoma (1 paper, 2013). A usually aggressive malignant bone-forming mesenchymal neoplasm, predominantly affecting adolescents and young adults. "Therefore, in our study, we aimed to assess the role of XPG, XPC, CCNH and MMS19L polymorphisms response to chemotherapy in osteosarcoma." (PMID 24353725, 2013).
triple-negative breast carcinoma (1 paper, 2020). An invasive breast carcinoma which is negative for expression of estrogen receptor (ER), progesterone receptor (PR), and human epidermal growth factor receptor 2 (HER2). "Previous studies have reported that high CDK7 expression, together with Cyclin H and MAT1, was associated with better prognosis in ER-positive breast cancer patients and worse prognosis in triple negative breast cancer patients." (PMID 32155786, 2020).
viral infection (1 paper, 2023). "The CNS is an important HIV reservoir, and CCNH regulate transcription by RNA polymerase II and participate in HIV-1 early elongation complex formation, supporting viral infection and replication in the CNS." (PMID 36992502, 2023).
cancer (13 papers, 2019 to 2025). A tumor composed of atypical neoplastic, often pleomorphic cells that invade other tissues. "In addition, the risk for cancer progression/recurrence increased significantly if CCNH–C5orf30 (P = 0.026) or ZMPSTE24–ZMYM4 (P = 0.024) was detected in the serum samples after treatment." (PMID 38537933, 2024). "The increasing research in CCNH is associated with the poor prognosis of most human cancers." (PMID 33777168, 2021). "Although data on the functional relevance of rs2230641 is lacking, the pleiotropic effects of CCNH confer biological plausibility to our hypothesis that CCNH variants may be involved in cancer susceptibility." (PMID 31374908, 2019). "The impact of cancer treatments was also found in the serum levels of CCNH–C5orf30: 97.1% (33/34) of patients with HCC experienced a drop in the serum levels of the transcript after cancer treatment." (PMID 38537933, 2024). "These factors, produced by amniotic stem cells, can regulate the expression of cancer cell proteins associated with the cell cycle, such as cyclin-dependent kinases (CDK2, CDK4, CDK6) and cyclins (cyclin D2, cyclin E1, cyclin H)." (PMID 32972410, 2020). "Carcinoma specimens were divided into cyclin H low expressers (score ≤ 2, n = 40) and cyclin H high expressers (score > 2, n = 16) according to the immunohistochemical staining results." (PMID 32694938, 2020). "CCNH-C5orf30 is also very frequent among different types of cancers and their corresponding cancer cell lines." (PMID 30705370, 2019). "A computer analysed the data and classified them using ML, generating the hypothesis that four of the fusion transcripts (MAN2A1-FER ≤ 40, CCNH-C5orf30 ≤ 38, SLC45A2-AMACR ≤ 41, and PTEN-NOLC1 ≤ 40) were associated with a high probability of cancer." (PMID 39941182, 2025). "Additionally, our data demonstrate that CCNH expression levels in different cancers are quite different, and CCNH probably becomes a biomarker for cancer identification." (PMID 33777168, 2021). "The role of CCNH in other cancers also remains to be explored." (PMID 33777168, 2021). "Besides, CCNH has been found to participate in many cancer progressions." (PMID 33777168, 2021). "Studies have previously shown that Cyclin H (CCNH) is involved in the tumorigenesis and development of many cancers." (PMID 33777168, 2021). "To expand our analyses of other fusion genes in the panel, we analyzed TRMT11-GRIK2, MTOR-TP53BP1, CCNH-C5orf30, KDM4-AC011523.2, TMEM135-CCDC67, and LRRC59-FLJ60017 in 20 cancer cell lines from six different human malignancies." (PMID 30705370, 2019). "It has been shown that Nic induces downregulation of CDK2 and CDK4, but not CDK7, cyclin D2 or cyclin H in other cancer types." (PMID 36304150, 2022). "Compared to the patients with no peritoneal metastasis, cyclin H expression was significantly increased in patients with malignant tumor cells in peritoneal fluid (P = 0.016)." (PMID 32694938, 2020). "In addition, we found that the levels of CCNH protein in various cancers were different, and the level of CCNH protein expression in each stage of LUAD was higher than normal." (PMID 33777168, 2021).
tumor (6 papers, 2010 to 2024). "Emerging evidence has indicated that abnormal expression or genetic polymorphism of cyclin H is associated with tumor progression and chemosensitivity." (PMID 32694938, 2020). "By immunohistochemical analysis of cyclin H expression in 95 tumour specimens of a single centre population we found a high expression of cyclin H (≥ 10% reactive cells) in 24% of the tumours, which correlated well with the risk of malignancy (p = 0.176)." (PMID 20598140, 2010). "Quantification of cyclin H expression by Real time PCR in normal intestinal tissue and in a relapse of a jejunal high risk GIST indicated that cyclin H transcription is increased by 10 fold in the tumour tissue." (PMID 20598140, 2010). "Of the 23 tumours stained positive for Cyclin H the distribution with regard to the different risk categories was as follows: 11 of 39 high risk GIST (28%), 4 of 19 intermediate risk (21%) and 8 of 35 low or very low risk GIST (23%)." (PMID 20598140, 2010). "Analysis of the relationship between nuclear cyclin H positivity and risk of malignancy according to Fletcher and co-workers revealed that high risk GIST tumours are 3 times more frequently cyclin H positive than very-low risk GIST (p = 0.176)." (PMID 20598140, 2010). "In this study, we investigated the expression pattern of cyclin H in a single-centre population of 95 GIST and evaluated its prognostic value, since our gene expression analysis in normal and tumour tissue of a high-risk GIST patient revealed a 10 fold upregulation of cyclin H in tumour tissue." (PMID 20598140, 2010). "Additionally, in patients with tumour recurrence and/or metastases, cyclin H positivity was significantly associated with reduced disease-specific survival (p = 0.016) regardless of risk-classification." (PMID 20598140, 2010). "Moreover, in patients with tumour recurrence and/or metastases, cyclin H positivity was significantly associated with reduced disease-specific survival (p = 0.016) regardless of risk-classification." (PMID 20598140, 2010). "We observed a significant association between OS and the expression of six genes (CCNH, MLH3, RAD51C, RPA3, SLK, and XPA) in primary tumor tissues." (PMID 37240218, 2023). "In primary tumor tissue, the string correlations among CCNH, XPA, and SLK are interesting: CCNH and its correlation with CDK7 and, last but not least, the correlation of CDK7 in strings with RAD51C and XPA." (PMID 37240218, 2023). "Our data showed that the CCNH protein expression level of LUAD patients was positively correlated with tumor grade, and the increase in CCNH protein expression level was positively correlated with the patient's gender." (PMID 33777168, 2021). "Based on the bioinformatics analysis of the CPTAC database, we constructed the relationship between the level of CCNH protein expression and the grade, gender, age, weight, and tumor stage of LUAD patients." (PMID 33777168, 2021). "The correlation of cyclin H with the clinical characteristics, prognosis, and the proliferation parameters of tumor patients were analyzed." (PMID 32694938, 2020). "In contrast, our data show a significant correlation of Cyclin H expression with reduced DSS in high risk GIST and in patients with metastases or tumour recurrence." (PMID 20598140, 2010). "Based on this high transcription level of cyclin H in one GIST, we analysed cyclin H expression at a protein level in the tumour tissue of the same patient." (PMID 20598140, 2010). "In patients who were affected by tumour recurrence or metastases, cyclin H positivity indicated a significantly lower disease-specific survival (e.g. 33.3% vs. 64.2% after 3 years, p = 0.016 log-rank test)." (PMID 20598140, 2010). "In the majority of these tumours the intensity was moderate positive (19/23) and only 5 tumours showed a very strong cyclin H staining." (PMID 20598140, 2010).
tumor (continued). "The cyclin H immunostaining pattern of tumours of 95 patients with GIST was characterised and correlated to clinicopathologic features and clinical outcome." (PMID 20598140, 2010). "However, the correlation between CCNH expression and tumor grade and the correlation between gender differences in LUAD patients had not been found yet." (PMID 33777168, 2021). "High cyclin H expression was significantly correlated with the increased tumor grade." (PMID 32694938, 2020). "Seven genes out of 13 (CCNH, ERCC2, ERCC6, NEIL1, OGG1, RPA1, XPA) had a significantly different expression in tumour versus normal tissue stored in PAXgene Tissue System." (PMID 27383461, 2016). "Consequently, immunohistochemical analysis of cyclin H expression in the tumour tissue of 95 GIST patients was undertaken and revealed nuclear positivity of cyclin H in 24% (n = 23) (cut-off value of ≥10% reactive cells)." (PMID 20598140, 2010). "After one year, 50% of the patients with cyclin H- and p16-positive high risk GIST died and none of these patients was tumour free in comparison to 98% survivors and 83% tumour-free patients in the control group." (PMID 20598140, 2010). "Simultaneous analysis of cyclin H and a previously investigated factor, p16, within an intersection sub-cohort revealed that the combined positivity of both parameters indicates poor outcome of GIST, irrespective of the mitotic rate or tumour size (p = 0.039)." (PMID 20598140, 2010).
infection (3 papers, 2016 to 2024). The state of being infected such as from the introduction of a foreign agent such as serum, vaccine, antigenic substance or organism. "A clear increase in the levels of cyclin H protein was observed upon infection with HCMV AD169-GFP (lanes 2–6)." (PMID 39195228, 2024). "In the next step, a primary human foreskin fibroblast (HFF) population with a stably transduced doxycycline (dox) inducible cyclin H-specific short hairpin RNA (shRNA) was generated and then used for qPCR-based infection kinetics." (PMID 39195228, 2024).
CCNH also shares sentences with these, for which no sentence is quoted: esophageal cancer (2 papers); glioblastoma (2); adenocarcinoma (1); bladder cancer (1); diffuse large B-cell lymphoma (1); endometrial cancer (1); esophageal adenocarcinoma (1); lymph node metastases (1); myeloid leukemia (1); non-small cell lung carcinoma (1); peripheral neuropathy (1); preeclampsia (1); Spastic paraplegia 7 (1); xeroderma pigmentosum group B (1).